GPX4 (glutathione peroxidase 4)
Diseases named in the same sentence as GPX4 in open-access papers (continued):
Sharing a sentence is not in itself a finding about the gene and the disease.
cancer (continued). "The nano-platform can induce ROS storms, depleting GSH, inactivating GPX4, and catalyzing LOX to promote irreversible cancer cell immunogenic ferroptosis." (PMID 38288118, 2023). "Abnormal expression of SLC7A11, GPX4, and AIFM2 was found in a variety of tumors, which can be used to evaluate the prognosis and invasion degree of various cancers." (PMID 37894808, 2023). "FSP1 and DHODH play a role in preventing ferroptosis, implicating them as promising targets for cancer therapy, particularly in cancers with relatively less functioning of the core ferroptosis regulatory system, xCT/GSH/GPX4." (PMID 37371948, 2023). "Selenium, as well as GPX4 levels, accordingly decrease upon knockout of LRP8, the latter being specific for cancer cells." (PMID 36658724, 2023). "GPX4 and system xc– are not only critical regulators of ferroptosis, but also exert a crucial effect on the TME, making them potential targets for cancer therapy." (PMID 37325669, 2023). "Consistent with an increased susceptibility to oxidative stress in DTP cells, another study reported that these cells rely on the expression of the glutathione peroxidase 4 (GPX4) in EGFR-mutant NSCLC, as well as in other different types of cancer." (PMID 36672453, 2023). "Inhibition the expression of HMGCR downregulate the mevalonate (MVA) pathway and glutathione peroxidase 4 (GPX4), thereby inducing cancer cell ferroptosis." (PMID 37770820, 2023). "GPX4 utilized GSH as a reducing cofactor that decreases hydroperoxide derivatives of lipids (PLOOH) to fatty alcohol, thereby suppressing ferroptosis in cancer cells." (PMID 37061535, 2023). "Luciferase reporter assay was conducted to examine the translation activity of GPX4 promoter, and immunohistochemistry (IHC) was conducted to analyze the levels of c-MYC, Ki-67 and AR in TQB3720-treated cancer tissues." (PMID 36744249, 2023). "GPX4 acts as a downstream of SLC7A11, and its expression is also increased, which contributes to cancer resistance to chemotherapy-induced ferroptosis." (PMID 37266741, 2023). "A majorly pan-cancer positive correlation between promotor methylation and gene expression of GSDMA, CASP1, NLRP9, GZMB, DHX9, DDX3X, SFRS2IP (CASP11) and GPX4 was observed." (PMID 36605187, 2022). "Significantly upregulated PRGs included PYCARD in 12 cancers; GSDMB in 10 cancers; IL18 in 9 cancers; GSDMD, CASP8, GZMB, and GPX4 in 8 cancers; AIM2 and CASP6 in 7 cancers; GZMA in 6 cancers; GSDME, CASP4 and DHX9 in 5 cancers; GSDMA and GSDMC in 4 cancers." (PMID 36605187, 2022). "Nevertheless, mechanisms of rewiring of the hierarchy have been described in cancer cells, dependent on SECIS element recoding efficiency and ribosome stalling during translation of GPX4 when Se levels are low, reducing GPX4 levels." (PMID 36358931, 2022). "Sometimes, these ncRNAs can directly target GPX4, SLC3A2 and SLC7A11 to induce ferroptosis in cancer cells." (PMID 35342359, 2022). "It has also been reported that the GPX4 inhibitors RSL3 and ML210 can disrupt the antioxidant system and ferroptosis in many drug-tolerant cancer cells (e.g., melanoma, breast, lung, and ovarian cancer cells) in vitro and prevent tumor relapse." (PMID 36009223, 2022). "GPX4, another member of the GPX family, is considered a modulator of ferroptotic cancer cell death, driven by lipid peroxide through inhibition of the cystine/glutamate transporter, and is reported to be important for the survival of TNBC cells." (PMID 35158912, 2022). "To date, many related pathways have been found to mediate ferroptosis in cancer cells, including system Xc-/GSH/GPX4, FSP1/CoQ10/NAD(P)H, and ATG5/ATG7/NCOA4 pathways, which are considered potential therapeutic targets, especially for the treatment of cancers." (PMID 36009223, 2022).
cancer (continued). "Based on function, the 12 FRGs can be grouped into four classes: Lipid metabolism (GPX4, LPCAT3, ACSL5, and ACSL6), antioxidant metabolism (CD44, SESN2, and AIFM2), iron metabolism (CISD1 and HSPB1), and cancer metabolism (SOCS1, FH, and G3BP1)." (PMID 34784264, 2022). "High GPX4 expression is correlated with poor clinical outcomes in patients with NPC and other cancer types." (PMID 35105963, 2022). "Subsequently, researchers examined the sensitivity of 117 cancer cells to erastin-induced ferroptosis cell death and found that RCC was particularly sensitive to GPX4-regulated ferroptosis." (PMID 35350243, 2022). "We identified GPX4 inhibitor-sensitive and resistant cell lines and compared NUAK2 expression, from Cancer Cell Line Encyclopedia RNA sequencing data, in these two groups." (PMID 35523770, 2022). "Later, in a study of cancer entities, pharmacological treatment with FSP1 and GPX4 inhibitors exerted a strong synergistic effect on inducing ferroptotic death." (PMID 36238649, 2022). "There are also reports that platinum‐tolerant cancer cells with FZD7+ had altered GSH metabolism, required GPX4 for survival, and were sensitive to eradication via ferroptosis." (PMID 36485069, 2022). "Inducing ferroptosis by either inhibition of the cystine/glutamate transporter, SLC7A11 (i.e., erastin) or glutathione peroxidase 4 (GPX4) (i.e., RSL3) has shown promising results in a variety of cancers." (PMID 36314903, 2022). "In addition, Fin56 can also induce GPX4 autophagic degradation and combined Fin56 with mTOR inhibitor enhances bladder cancer cell ferroptosis, suggesting that the combination of autophagy and ferroptosis inducers could effectively enhance cancer therapy." (PMID 36289191, 2022). "We found that a significant decrease of GPX4 activity was observed for Zn2+ or Zn-Fu MNs treated cancer cells, in contrast to PBS or Fu group, suggesting the great inactivation of GPX4, induced by Zn2+ or Zn-Fu MNs." (PMID 36168615, 2022). "As for OV, the possible connection between ferroptosis and cancer was mainly bridged through three “musketeers”: the FSP1-CoQ10 protection pathway, GPX4-GSH protection pathway, and GCH1-BH4 protection pathway." (PMID 36685851, 2022). "Analysis of 21 different types of cancer in 7462 cancer samples showed that both SLC7A11 and GPX4 are overexpressed in colorectal cancer (CRC)." (PMID 35280777, 2022). "As a result, large amount of reactive oxygen species (ROS) would be produced, resulting in the break of redox balance within cancer cells 47-49, elimination of overexpressed glutathione (GSH) and the inactivation of glutathione peroxidase 4 (GPX4) protein." (PMID 36168615, 2022). "GPX4 is a key regulator of ferroptosis that inhibits COX and lipoxygenase (LOX) activities by reducing lipid peroxidation levels in cancer cells." (PMID 36400758, 2022). "The results showed that certain genes (such as GPX4, SLC7A11 and GSS) displayed higher expression, while others (such as ACSL1 and ACSL4) displayed lower expression in some cancer types." (PMID 34975326, 2022). "The ROS generation and GPX4 inactivation led to lipid oxidation and MDA accumulation in cancer cells." (PMID 36168615, 2022). "The pharmacological inhibition of system xc− or GPX4 by small molecule compounds (RSL3 and erastin) is a classic model for inducing ferroptotic cancer cell death." (PMID 36274088, 2022). "In agreement, other studies also indicated that mTORC1 activation led to ferroptosis resistance in multiple contexts of cancer, albeit likely involving mechanisms besides MUFA production, such as increased expression of the GPX4 protein." (PMID 36282248, 2022). "The 12 FRGs are divided into 4 categories according to their functions: lipid metabolism (GPX4, LPCAT3, ACSL5, ACSL6), antioxidant (CD44, SESN2, AIFM2), iron metabolism (CISD1, HSPB1), and cancer metabolism (SOCS1, FH, G3BP1)." (PMID 35559049, 2022).
cancer (continued). "The recent finding of the prioritization GPX4, TXNRD1, and SEPHS2 synthesis in cancer cells, favoring a cell proliferative phenotype, repurposes the selenoprotein synthesis hierarchy in cancer cells." (PMID 36358931, 2022). "It has been shown that ferroptosis suppression in cancer is connected with the activation of the system Xc− importer, elevations in GSH metabolism and Gpx4 action, as well as suppression of OS and Fe metabolism." (PMID 35408533, 2022). "Among the 4 cancer cell lines, K1 cells exhibited higher GPX4 gene expression relative to MDA-T32, MDA-T68, and TPC-1 cancer cells and control HThF." (PMID 36371529, 2022). "It has been demonstrated that SLC7A11 confers resistance to ferroptosis in cancer cells by importing cystine for the synthesis of GSH and indirectly relieving lipid ROS stress by activating the essential enzyme GPX4 to reduce lipid hydroperoxides." (PMID 34568075, 2021). "Recent studies identified RSL3, an inhibitor of glutathione peroxidase-4 (GPX4), as an efficient inducer of ferroptotic cell death in cancer cells." (PMID 33432112, 2021). "Thus, GPX4 may act as a central repressor of ferroptosis in cancer cells." (PMID 34778060, 2021). "The Cancer Genome Atlas (TCGA) data analysis showed that BCAT2 expression correlated with cancer grade and the expression of ferroptosis markers (GPX4 and NCOA4) in HCC." (PMID 33097833, 2021). "However, overexpression of GPX4 could also benefit cancer cells." (PMID 33821873, 2021). "We also analyzed the prognostic values of SLC7A11, GPX4, and AIFM2 in pan-cancer using Kaplan–Meier database." (PMID 34722530, 2021). "Next, we analyzed the prognostic values of SLC7A11, GPX4, and AIFM2 in pan-cancer using GEPIA database." (PMID 34722530, 2021). "We further investigated the relationships between the expression levels of SLC7A11, GPX4, and AIFM2 and immune infiltration levels in pan-cancer by using the TIMER database." (PMID 34722530, 2021). "Some genes were expressed at similar levels in different types of cancer, including GPX1, GPX4, TXNRD1, TXNRD2 and TXNRD3." (PMID 33706760, 2021). "Our study showed that GPX4 activity is decreased in MDA-MB-231 and A375 cancer cells as treated with low-level laser irradiation and GA compare to control groups." (PMID 31956296, 2020). "However, GPX4 inhibitors do not always cause cell death in cancer cell lines." (PMID 32516941, 2020). "Notably, we and others have recently identified a GPX4-dependent state in therapy-resistant cancer cells, including therapy-induced persister cells, that in general resist apoptotic death otherwise induced by the main modalities of cancer treatments—chemotherapy, targeted therapy, and immunotherapy." (PMID 30962421, 2019). "When we used E-cadherin/β-actin ratio to correlate the IC50s, we observed that mesenchymal-high (i.e., low E-cadherin/β-actin ratio) cancer cells exhibited significantly enhanced sensitivity (i.e., low IC50) to GPx4 inhibitor ML162." (PMID 31527591, 2019). "ALDH1A1-induced upregulation of SOD2 and GPX4, as well as ALDH1A1 itself, mitigates erlotinib-induced oxidative and carbonyl stress in cancer cells and imparts erlotinib resistance." (PMID 31695757, 2019). "We treated cancer cells with RSL3, which induces ferroptosis via the inhibition of GPX4, which is an ROS scavenger." (PMID 30988278, 2019). "In German patients, GPX1, GPX4, and TXNRD1 were also found to be up-regulated in cancer, compared to the matched tissues for mRNA and/or their corresponding protein levels." (PMID 30469315, 2018). "In addition to GPX4, inhibition of an increasing number of key molecules has been related to ferroptosis, which may induce cell death and eradicate chemotherapy/radiotherapy-resistant cancer cells." (PMID 29375387, 2017).
cancer (continued). "There is one SNP (rs11574359), two genes (GPX4 and SIRT3) and one pathway (FoxO) that demonstrated age-related patterns of survival in cancer patients and will be discussed in turn." (PMID 29064820, 2017). "Discovery of the inhibitor NF611 selectively abolished GPX4 levels in cancer cells without impacting GPX4 levels in T cells or NK cells." (PMID 41139700, 2026). "Additionally, an overlap in gene signatures between GPX4 and LRP8-overexpressing cancer cells was found." (PMID 41139700, 2026). "Importantly, systemic comorbidities such as diabetes converge on redox regulators including GPX4, linking metabolic stress to enhanced RAX reliance across multiple cancers." (PMID 41462674, 2025). "POR deficiency enhances resistance to drug-induced ferroptosis and decreases lipid peroxides without influencing the glutathione or GPX4 amount in most cancer cells." (PMID 40724837, 2025). "Extensive research has been conducted on the role of METTL16 in regulating cancer progression through m6A modification of target genes, including U6 snRNA, MALAT1, XIST, and RAB11B‐AS1, and mRNA (MAT2A, VPS33B, FGFR4, and GPX4)." (PMID 40095756, 2025). "In addition, a recent study demonstrated that exogenous CO can regulate ROS and GPX4 levels to promote ferroptosis in NSCLC, suggesting a novel therapeutic strategy for cancer treatment." (PMID 40066170, 2025). "To address this, we explored whether simultaneous inhibition of GLS1, GPX4 and GPX1 could synergistically inhibit cancer cell growth." (PMID 40259435, 2025). "In our studies using Ras/Raf mutant cancer cells, co-treatment with the ferroptosis inhibitor Ferrostatin-1 rescued EC359-induced cell death, and Western blot analysis confirmed downregulation of the ferroptosis regulator GPX4." (PMID 41154625, 2025). "The heatmap displayed that GPX4 expression was highly correlated with the levels of numerous chemokines and chemokine receptors, such as CXCL16, CCL28, CX3CL1, CCL5, CCR10, CXCR5, and CXCR3, across the majority of cancer types." (PMID 41142608, 2025). "In cancer treatment, RAS-selective lethal small molecule 3 (RSL3), a ferroptosis-specific inducer, demonstrates antitumor efficacy by inducing ferroptosis in colorectal cancer via GPX4 inactivation and ROS production." (PMID 41471274, 2025). "Cancer cells escaping treatment can enter a non-genetic state of persistence, and such persister cells tend to develop a dependency on GPX4 activity for survival." (PMID 40301648, 2025). "Furthermore, gene interactions between cuproptosis regulators (e.g., FDX1, DLAT) and ferroptosis regulators (e.g., GPX4, SLC7A11) emphasize their interaction, highlighting potential therapeutic strategies that target mitochondrial vulnerabilities in cancers." (PMID 39949740, 2025). "Recent drug screening has identified N6F11, a previously uncharacterized small molecule that selectively degrades GPX4 in cancer cells without affecting DCs, T cells, or NK cells." (PMID 41326356, 2025). "The production of GPX4 and other selenoproteins is highly dependent on SEPHS2, and SEPHS2 has been shown to be a potential target for cancer therapy because of its important role in cancer cell survival." (PMID 41049288, 2025). "Notably, interactions among ferroptosis-related pathways, especially GPX4, NRF2, and iron metabolism regulators, are pivotal in cancer drug resistance." (PMID 39935430, 2025). "They induce autophagic cell death, which reduces cancer cell survival, and promote ferroptosis, an iron‐dependent cell death mechanism, by inhibiting the Glutathione/Glutathione Peroxidase 4 (GSH/GPX4) pathway, leading to increased lipid peroxidation and oxidative stress in cancer cells." (PMID 40387523, 2025). "The combination of DHODH knockdown and GPX4 inactivation, but not either alone, substantially induced mitochondrial lipid peroxidation and ferroptosis in cancer cells, which was reversed by the restoration of GPX4mito but not GPX4cyto98." (PMID 40083691, 2025).
cancer (continued). "Moreover, activated CD8+ T cells secreted interferon γ (IFN-γ), which inhibits GPX4 and other GSH-dependent enzymes, leading to ferroptosis in cancer cells." (PMID 40140647, 2025). "GPx1 and GPx4, which are key antioxidant enzymes that protect cancer cells from apoptosis and ferroptosis, do not contain canonical AREs and are not considered direct targets of NRF2." (PMID 40818321, 2025). "More recent studies indicate that the GPX4‐mediated antiferroptosis effect can be suppressed by tripartite motif 36 (TRIM36), low‐dose antimony treatment, or AR inhibition, which reverses the NET process and has demonstrated effectiveness in treating cancers." (PMID 40900810, 2025). "This may be attributed to GPX4's modifications of N6-methyladenosine (m6A) and 5-methylcytosine (m5C), which activate STING and help maintain redox balance during cancer immunotherapy, thereby facilitating immune regulation." (PMID 40365295, 2025). "have shown that selenium‐avid cancer cells employ SLC7A11 (a constituent of the cystine/glutamate antiporter SLC7A11) and xCT to facilitate increased selenium uptake, This, in turn, enables cancer cells to synthesize GPX4." (PMID 41323827, 2025). "In addition, the depletion of GSH is an important factor leading to the inactivation of glutathione peroxidase 4 (GPX4, a ferroptosis inhibition protein), which significantly decreases the scavenging of LPO, inducing cancer cell ferroptosis." (PMID 40567832, 2025). "Dual targeting of GPX4 and GPX1 presents a potent anti‐cancer strategy." (PMID 40259435, 2025). "Furthermore, combination therapies targeting GPX4 and FAK/Src were found to enhance cancer cell death, and MDM2, ezrin, and cortactin were identified as potential ferroptosis inhibitor targets." (PMID 40164758, 2025). "This aligns with reports that STAT3 represses SLC7A11/GPX4 in non-malignant settings but promotes ferroptosis resistance in cancer." (PMID 41515376, 2025). "However, cancer cells can develop resistance by upregulating ferroptosis defense mechanisms, such as SLC7A11 and GPX4, to promote survival during radiotherapy." (PMID 41213903, 2025). "Notably, we found that GPX4 expression was positively correlated with M2 macrophages in the TME, suggesting its potential role in promoting oncogenesis in these cancers." (PMID 41142608, 2025). "Anyway, targeting the FSP1/Coenzyme Q10 axis to induce ferroptosis in cancers, especially those that do not rely on GPX4-related mechanisms to tackle ferroptosis, appears to be a promising strategy." (PMID 40227202, 2025). "Besides GPX4 and FSP1, another key regulator of ferroptosis resistance is AMP-activated protein kinase (AMPK), which exhibits dual roles across various cancers." (PMID 39935430, 2025). "Inhibition of GPx4 fails to trigger ferroptosis in some cancer cell lines, and cells proliferate indefinitely." (PMID 39201524, 2024). "We will focus on GPX4 and GPX1 because of their important roles in cancer." (PMID 39061847, 2024). "In cancers, the crucial expression of FSP1 can predict the effectiveness of iron apoptosis-inducing medications, which function alongside the traditional glutathione-dependent GPX4 pathway as a strong inhibitor of ferroptosis." (PMID 38563866, 2024). "In colon cancer cells, HNK increased ROS and Fe2+ levels by decreasing the GPX4 activity without influencing system Xc− to induce ferroptosis, thus reducing cancer cell viability." (PMID 39021832, 2024). "As a key regulator of ferroptosis, Gpx4 may be a potential target for BBR to promote ferroptosis and exert anti-cancer effects." (PMID 38957396, 2024). "For instance, cancer cells treated with palladium pyrithione complex (PdPT), which acts as a pan-deubiquitinase (pan-DUB) inhibitor, experience apoptosis and ferroptosis characterized by caspase activation and degradation of the GPX4 protein." (PMID 39595619, 2024).